PLEKHA4 (pleckstrin homology domain containing A4)
Description:
Binds specifically to phosphatidylinositol 3-phosphate (PtdIns3P), but not to other phosphoinositides.
Synonyms: PEPP1
Tractability: Antibody: UniProt places it where antibodies can reach, with high confidence; its Gene Ontology location is reachable by antibodies, with high confidence; the Human Protein Atlas places it where antibodies can reach.
Gene: Protein-coding gene on chromosome 19 (48,837,091 to 48,868,855, reverse strand). Ensembl gene ENSG00000105559.
Subcellular location: Cytoplasm; Membrane
Subcellular location (Human Protein Atlas): Cytosol; Plasma membrane; Centriolar satellite; Cytokinetic bridge
Pathways (Reactome):
Metabolism: Synthesis of PIPs at the plasma membrane
Gene Ontology:
Molecular function: phosphatidylinositol-3,4-bisphosphate binding; phosphatidylinositol-3,5-bisphosphate binding; phosphatidylinositol-3-phosphate binding; phosphatidylinositol-4,5-bisphosphate binding; protein binding
Biological process: positive regulation of canonical Wnt signaling pathway; positive regulation of Wnt signaling pathway, planar cell polarity pathway; phosphatidylinositol biosynthetic process
Cellular component: extrinsic component of cytoplasmic side of plasma membrane; plasma membrane; cytoplasm; membrane
Genetic constraint (gnomAD): Loss-of-function variants: 62 observed, 85.25 expected, observed/expected ratio (o/e) 0.73, 90% interval 0.59 to 0.9. The upper end of that interval is the gene's LOEUF score, 0.9, which puts it in group 3 of 6, group 1 being the genes least tolerant of losing a copy. Missense variants: 973 observed, 1,006.1 expected, observed/expected ratio (o/e) 0.97, 90% interval 0.92 to 1.02. Synonymous variants: 408 observed, 416.83 expected, observed/expected ratio (o/e) 0.98, 90% interval 0.9 to 1.06.
Homologues: Orthologues: chimpanzee PLEKHA4 (99% identical), macaque PLEKHA4 (97% identical), dog PLEKHA4 (87% identical), guinea pig PLEKHA4 (83% identical), mouse Plekha4 (80% identical), rat Plekha4 (80% identical), pig PLEKHA4 (74% identical), rabbit PLEKHA4 (65% identical), tropical clawed frog plekha4 (36% identical), zebrafish si:ch211-234p6.5 (23% identical). Paralogues in human: PLEKHA7 (32% identical), PLEKHA5 (24% identical), PLEKHA6 (23% identical).
Diseases named in the same sentence as PLEKHA4 in open-access papers:
PLEKHA4 is named in the same sentence as 38 diseases in open-access papers, as found by Europe PMC text mining. Sharing a sentence is not in itself a finding about the gene and the disease. The quoted sentences say what the papers report.
breast carcinoma (4 papers, 2022 to 2024). "Our data revealed that the low expression of PLEKHA4 in patients with menopause below 50 years correlated with a higher risk of breast cancer." (PMID 38859961, 2024). "The analysis showed that the expression of PLEKHA4 was upregulated in central nervous system neoplasms, breast cancer, head and neck cancer, and melanoma and downregulated in bladder cancer and ovarian cancer." (PMID 36714030, 2023). "To investigate the expression of three genes, NR1H3, PLEKHA4, and THEM6, in breast carcinoma, we analyzed multiple independent cohorts, including three GEO cohorts as well as the cBioPortal database." (PMID 38081884, 2023). "PLEKHA4 was a prognostic marker in various TCGA cohorts, including cancers with high immunogenicity, immune infiltration, and TMB, including pancreatic adenocarcinoma, breast cancer, thyroid carcinoma, and hepatocellular liver carcinoma (including LGG)." (PMID 36408463, 2022).
glioma (4 papers, 2022 to 2025). A benign or malignant brain and spinal cord tumor that arises from glial cells (astrocytes, oligodendrocytes, ependymal cells). "We downloaded datasets from TCGA and carried out analysis by R-3.6.3 for the purpose of further investigating the underlying mechanisms and relationships of PLEKHA4 expression in gliomas." (PMID 36714030, 2023). "Recently, PLEKHA4 was reported to be upregulated in melanoma and closely associated with tumor genesis and development, but its role in glioma is poorly understood." (PMID 36714030, 2023). "Taken together, our findings indicate that upregulation of PLEKHA4 expression is associated with poor prognosis and tumor immune infiltration in glioma." (PMID 36714030, 2023). "We downloaded the clinical data of glioma patients from the TCGA database and then used the Wilcoxon rank sum test to analyze the association between PLEKHA4 expression level and clinicopathological variables." (PMID 36714030, 2023). "The relationships between the expression of PLEKHA4 and different immune cells or immune cell biomarkers implicated that PLEKHA4 might play an important role in regulating tumor immune microenvironment of glioma." (PMID 36714030, 2023). "Knockdown experiments showed reduced glioma cell proliferation, and drug sensitivity analysis suggests potential for targeting PLEKHA4 with kinase inhibitors." (PMID 40565099, 2025). "The ssGSEA analysis indicated a substantial positive connection of PLEKHA4 expression with infiltration levels of macrophages, neutrophils, T cells, NK cells, and so on in glioma." (PMID 36714030, 2023). "Our results highlighted that PLEKHA4 mRNA expression was associated with age, IDH mutation status, 1p19q codeletion status, histological type, and the tumor grade in glioma patients." (PMID 36714030, 2023). "To further evaluate the role of PLEKHA4 in tumor immunity, we determined the correlation of PLEKHA4 expression with immune cell biomarkers in glioma by GEPIA database." (PMID 36714030, 2023). "In this study, we also assessed the immune infiltration based on the expression level of PLEKHA4 and discovered that most immune cells are positively connected with the expression of PLEKHA4 in glioma." (PMID 36714030, 2023). "The results of this study indicated that PLEKHA4 expression was a prognostic factor and related to the clinicopathological characteristics of glioma patients." (PMID 36714030, 2023). "In this study, we found the correlation of PLEKHA4 expression with survival of glioma patients using GEPIA, an online database." (PMID 36714030, 2023). "Our aim was to investigate the expression, functional role, and prognostic value of PLEKHA4 in glioma." (PMID 36714030, 2023). "Then, we downloaded datasets of glioma from TCGA and investigated the correlations between the clinical characteristics and PLEKHA4 expression using logistic regression." (PMID 36714030, 2023). "Glioma tissue microarrays were adopted to verify the expression patterns of PLEKHA4 and PD-L1 in clinical LGG specimens." (PMID 37818357, 2023). "So we assessed the correlation between the expression of PLEKHA4 and the infiltration level of 6 immune cells in glioma through TIMER." (PMID 36714030, 2023). "Meanwhile, we found that high PLEKHA4 expression in glioma patients from the TCGA database was significantly related to worse histological grade and shorter OS, DSS, and PFI." (PMID 36714030, 2023). "PLEKHA4 transcript levels were significantly upregulated in multiple cancer types, including gliomas." (PMID 36714030, 2023). "Given that the potential carcinogenic effects of PLEKHA4 in glioma, the relationships between glioma and PD1, PD-L1, CTLA-4, and TIM-3 were analyzed." (PMID 36714030, 2023). "To this end, we identified the expression profile and prognostic significance of PLEKHA4 in gliomas based on public data as well as clinical samples." (PMID 37818357, 2023).
glioma (continued). "As a result, we performed and studied the potential value of PLEKHA4 in glioma, which was the first to analyze the expression of PLEKHA4 in a large number of human glioma patients." (PMID 36714030, 2023). "Meanwhile, IHC results provided by the HPA database also displayed that PLEKHA4 protein, which was mainly distributed in the cytoplasm and membrane, was obviously elevated in both low grade and high-grade gliomas, compared with normal brain tissue." (PMID 37818357, 2023). "In the present study, we explored the expression levels of PLEKHA4 in 20 types of human cancers and corresponding normal tissue and unearthed the prognostic value of PLEKHA4 in glioma based on data from The Cancer Genome Atlas (TCGA)." (PMID 36714030, 2023). "As far as we know, there is no more literature that described the potential prognostic impact of PLEKHA4 in other tumor, including glioma." (PMID 36714030, 2023). "Here, we detected that PLEKHA4 protein was localized to the cytoplasm, and the expression of PLEKHA4 in glioma tissues was significantly higher than that in adjacent normal tissues by immunohistochemical staining and HPA online tool." (PMID 36714030, 2023). "Gene Set Enrichment Analysis was performed to explore glioma involved signaling pathways between low and high PLEKHA4 expression groups." (PMID 36714030, 2023). "These all suggested that PLEKHA4 may serve as a potential prognostic marker of prognosis and therapeutic target in glioma." (PMID 36714030, 2023). "Furthermore, we determined the potential relationship between PLEKHA4 and immune cell infiltration, immune cell biomarkers, or immune checkpoints in the glioma microenvironment through the tumor immunity estimation resource (TIMER)." (PMID 36714030, 2023). "PLEKHA4 expression was associated with age (P < 0.001), WHO grade (P < 0.001), IDH mutation status (P < 0.001), 1p19q codeletion status (P < 0.001), and histological type (P < 0.001) in glioma patients." (PMID 36714030, 2023). "The protein expression of PLEKHA4 was strikingly elevated in glioblastoma samples (P<0.001), indicating that PLEKHA4 may play a vital role in the tumorigenesis of glioma." (PMID 37818357, 2023). "Moreover, we used TIMER to explore the collection of PLEKHA4 expression and immune infiltration level in glioma and to analyze cumulative survival in glioma." (PMID 36714030, 2023). "Our findings proposed that PLEKHA4 was an independent prognostic biomarker and correlated with immune infiltrates in glioma, and targeting PLEKHA4 might improve immunotherapy in glioma." (PMID 36714030, 2023). "The results showed that the upregulation of PLEKHA4 expression was significantly related to PD-1/PD-L1, CTLA4, and TIM-3 in glioma, indicating that targeting PLEKHA4 may improve immunotherapy in glioma." (PMID 36714030, 2023). "Moreover, immunohistochemical analysis verified that PLEKHA4 was overexpressed in gliomas compare to the corresponding normal tissues." (PMID 36714030, 2023). "We assessed the influence of PLEKHA4 on survival of glioma patients by survival module and GEPIA." (PMID 36714030, 2023). "Moreover, HPA database analysis indicated that PLEKHA4 protein staining which was positive in the highly malignant glioma cells was higher compared to the normal neuropil area." (PMID 36714030, 2023). "Also, possible key pathways in glioma that were regulated by PLEKHA4 were the chemokine signaling pathway, immune response, JAK STAT signal pathway, and cell cycle." (PMID 36714030, 2023). "However, the prognostic significance of PLEKHA4 and its correlation with immune infiltrates in glioma remain unclear." (PMID 36714030, 2023). "In summary, PLEKHA4 might serve as a favourable prognostic factor for patients with glioma." (PMID 36714030, 2023). "The results showed that the expression of PLEKHA4 was positively correlated with the infiltration level of B cells, CD8+ cells, CD4+ T cells, macrophages, dendritic cells, and neutrophils in glioma." (PMID 36714030, 2023).
glioma (continued). "The results showed that PLEKHA4 expression was positively correlated with B cell, CD4+ T cell, CD8+ Tcell, macrophage cell, neutrophil cell, and dendritic cell in glioma." (PMID 36714030, 2023).
melanoma (3 papers, 2021 to 2023). A malignant, usually aggressive tumor composed of atypical, neoplastic melanocytes. "Upregulated PLEKHA4 promotes Wnt/β-catenin signaling-mediated G1/S transition and proliferation in melanoma." (PMID 36714030, 2023). "PLEKHA4 can accelerate the proliferation of melanoma cells and the transition of the G-S cell cycle." (PMID 36408463, 2022). "It has been reported that PLEKHA4 is highly expressed in melanoma." (PMID 36714030, 2023). "Knockout of PLEKHA4 in nude mice can inhibit the growth of melanoma." (PMID 36408463, 2022). "One study about Melanoma found that, PLEKHA4 was required for melanoma proliferation and survival, PLEKHA4 knockdown could attenuate tumor growth and enhance the effect of clinically used inhibitor encorafenib." (PMID 34949987, 2021). "PLEKHA4, phosphoinositol 3-phosphate-binding protein 1 (PEPP1), promotes wnt/β-catenin signaling-induced G-S transition and proliferation in patients with melanoma." (PMID 36408463, 2022).
glioblastoma (2 papers, 2023). The most malignant astrocytic tumor (WHO grade IV). "PLEKHA4 at protein level was also greatly upregulated in glioblastoma as compared with normal tissues." (PMID 37818357, 2023). "PLEKHA4 was significantly upregulated in glioblastoma (Sun brain and Lee brain) compared to the corresponding normal tissue samples." (PMID 36714030, 2023). "Similarly, multivariate analysis showed that high PLEKHA4 expression positively correlated with age over 60, tumor WHO grades IV, IDH wild type status, and high-grade glioblastoma (GBM)." (PMID 36714030, 2023).
pancreatic adenocarcinoma (2 papers, 2022 to 2023). "Specifically, PLEKHA4 expression was significantly elevated in CHOL, diffuse large B-cell lymphoma (DLBC), GBM, KIRC, KIRP, LGG, pancreatic adenocarcinoma (PAAD), skin cutaneous melanoma (SKCM), STAD, testicular germ cell tumors (TGCT), THCA, and thymoma (THYM)." (PMID 37818357, 2023).
Alzheimer disease (1 paper, 2023). A progressive, neurodegenerative disease characterized by loss of function and death of nerve cells in several areas of the brain leading to loss of cognitive function such as memory and language. "Moreover, rs429358 and rs481778 located in APOE and PLEKHA4 genes on chromosome 19 are related to Alzheimer disease." (PMID 36859360, 2023).
astrocytoma (1 paper, 2023). "Meanwhile, PLEKHA4 expression was significantly different among subgroups stratified by histological type (P<0.001) and primary therapy outcome (P<0.001), and patients of astrocytoma (A) or progressive disease (PD) types usually have higher PLEKHA4 expression levels." (PMID 37818357, 2023).
autism spectrum disorder (1 paper, 2021). A spectrum of developmental disorders that includes autism, and Asperger syndrome. "It’s known that PLEKHA4 is involved in autism spectrum disorder." (PMID 34949987, 2021).
gastric cancer (1 paper, 2024). A primary or metastatic malignant neoplasm involving the stomach. "The hub proteins identified, CAT, PLEKHA4, HSP90AB1, TXN, EEF2, H6PD, and PDIA3, may play important roles in the treatment of gastric cancer using nintedanib." (PMID 38406279, 2024).
tumor (6 papers, 2020 to 2025). "Elevated pleckstrin homology domain containing A4 (PLEKHA4) expression, driven by DNA hypomethylation, is linked to tumor progression, WNT signaling, immune cell infiltration, and stemness maintenance." (PMID 40565099, 2025). "As a result, univariate analysis revealed that PLEKHA4 expression related to age, tumor WHO grades, IDH mutation status, 1p19q codeletion status, and histological type." (PMID 36714030, 2023). "We found that PLEKHA4 levels are associated with infiltration and differentiation of various tumor immune cells and the PD-L1 expression PD-1 checkpoint pathway." (PMID 36408463, 2022). "Through ESTIMATE calculation, we found that PLEKHA4 levels are closely associated with tumor immune infiltration." (PMID 36408463, 2022). "We also analyzed the association between PLEKHA4 levels in different tumors, patient prognosis, and its role in tumor immunity." (PMID 36408463, 2022). "Our present study comprehensively analyzed the relationship between the expression levels of PLEKHA4 and prognostic risk of LGG patient and determined the correlations between PLEKHA4 levels and tumor immune infiltrations." (PMID 36408463, 2022). "The tumor immune infiltration and clinical prognostic analyses showed that PLEKHA4 is associated with immune infiltration and prognostic outcomes for various cancers, including LGG." (PMID 36408463, 2022). "ssGSEA were further applied to analyze the correlation between PLEKHA4 expression and tumor-infiltrating immune cells." (PMID 37818357, 2023). "To detect the expression profiles of PLEKHA4 in common human cancers, we evaluated the mRNA expression of PLEKHA4 in various tumor and normal tissues in TCGA dataset using TIMER2.0." (PMID 37818357, 2023). "Univariable survival and multivariate cox analysis show that increased PLEKHA4 expression significantly correlated with age, tumor grade, IDH mutation status, and 1p/19q codel status, and higher PLEKHA4 had shorter OS, DSS, and PFI." (PMID 36714030, 2023). "Similar results were also acquired in CGGA-LGG (mRNAseq_325) cohort, implying that samples in the high PLEKHA4 group contained greater tumor-infiltrating immune cells and stromal cells." (PMID 37818357, 2023). "PLEKHA4 was manifested to substantially intervene in tumor immunity, prompting us to gain insight into its clinical significance in predicting immunotherapy response." (PMID 37818357, 2023). "Pleckstrin homology domain-containing family A member 4 (PLEKHA4) has been reported to be related to tumor invasion and growth." (PMID 36408463, 2022). "According to GSEA enrichment findings, we used ESTIMATE algorithm to establish the relationship between PLEKHA4 levels and immune, stromal, estimate scores, and tumor purity in LGG." (PMID 36408463, 2022). "We built a prognostic nomogram to better predict LGG prognosis by integrating two independent mortality predictors (tumor grade and PLEKHA4 levels) into the multivariate Cox regression model." (PMID 36408463, 2022). "First, we downloaded TCGA and GTEX data through USCS to assess PLEKHA4 levels in all normal and tumor tissues and found that PLEKHA4 was elevated in most tumors, such as LGG." (PMID 36408463, 2022). "We found that the expression of PLEKHA4 increased with the patient's age and the tumor's grade (all p < 0.05)." (PMID 36408463, 2022). "Immunohistochemistry was used to verify PLEKHA4 expression in tumor tissues." (PMID 36714030, 2023). "Additionally, the potential link between PLEKHA4 expression and infiltrating immune cells, CAFs, as well as tumor-related soluble factors, was examined through the ESTIMATE, ssGSEA, TIMER and CIBERSORT algorithm." (PMID 37818357, 2023). "Patients with higher PLEKHA4 expression have poorer tumor treatment responses." (PMID 36408463, 2022). "PLEKHA4 (pleckstrin homology domain containing A4) might be involved in the progression of a tumor through the Wnt pathway." (PMID 33043022, 2020).